ALB (albumin)
Diseases named in the same sentence as ALB in open-access papers (continued):
Sharing a sentence is not in itself a finding about the gene and the disease.
renal cell carcinoma (35 papers, 2012 to 2026). "Previous studies have shown that preoperative serum albumin levels is associated with human cancer survival, including renal cell carcinoma." (PMID 37165423, 2023). "Growing evidence has revealed that pretreatment C-reactive protein to albumin ratio (CAR) are associated with prognosis for patients with renal cell carcinoma (RCC)." (PMID 31644587, 2019). "Previous studies have shown that albumin-related systemic inflammation is associated with the long-term prognosis of cancer, but the clinical significance of an early (≤ 7 days) post-operative serum albumin level has not been well-documented as a prognostic factor in patients with renal cell cancer." (PMID 30522461, 2018). "Background/Objectives: To evaluate the utility of the addition of C-reactive protein/albumin ratio (CAR) to the International Metastatic Renal Cell Carcinoma Database Consortium (IMDC)." (PMID 42122209, 2026). "The role of the c-reactive protein to albumin ratio (CAR) as a predictor of poor prognosis in renal cell carcinoma (RCC) remains insufficiently recognized." (PMID 41566198, 2026). "This dataset displays results from preoperative muscle composition analysis and albumin levels in a large cohort (n = 473) of patients undergoing surgery for renal cell carcinoma." (PMID 36426052, 2022). "This multi-institutional study sought to clarify the association between the preoperative serum albumin/globulin ratio (AGR) and the prognosis of renal cell carcinoma (RCC) in a large cohort." (PMID 32686760, 2020). "Haemoglobin, albumin, lymphocyte, neutrophil, and platelet values that can be quickly determined in blood samples provide information about patients’ nutritional and inflammatory conditions, as emphasised in many studies on renal cell carcinoma." (PMID 40095849, 2025). "Indeed, CRP albumin ratio (CAR), consisting of CRP and albumin, has been confirmed as a useful prognostic factor in many cancer types, including gastrointestinal, lung, and urological such as renal cell carcinoma." (PMID 37333829, 2023). "In lung and renal cell cancer patients, we found that the Fearon consensus criteria, WLGS, NLR, albumin and PNI generally predicted worse disability‐free, hospitalization‐free and overall survival." (PMID 39817619, 2025). "In renal cell carcinoma, grade, TNM staging, albumin and lactate dehydrogenase (LDH), were among the strongest prognostic predictors by multivariate analysis." (PMID 26717416, 2015). "C-reactive protein (CRP), a serum marker for systemic inflammation, has shown good prognostication in patients with renal cell carcinoma (RCC) and similar findings when combined with serum albumin levels in the modified Glasgow Prognostic Score." (PMID 25006517, 2014). "Indeed, in renal cell carcinoma, CRP had a higher area under the curve for predicting OS compared with albumin." (PMID 36096761, 2022).
ulcerative colitis (35 papers, 2010 to 2026). An inflammatory bowel disease involving the mucosal surface of the large intestine and rectum. "In another study, the association between the CRP/albumin ratio and therapy responsiveness was assessed among patients with severe acute ulcerative colitis." (PMID 33193910, 2020). "Baseline hemoglobin (g/dL), C-reactive protein (CRP) (mg/L), albumin (gm/dL), and ulcerative colitis endoscopic index of severity (UCEIS) were 11±1.18, 121.2±76.8, 2.32±0.49, and 4.75±0.5, respectively." (PMID 39544600, 2024). "In univariate analyses, preoperative antibiotics use, ulcerative colitis diagnosis, lower albumin levels at admission, and preoperative hospital stay longer than seven days were associated with more severe postoperative complications." (PMID 37878974, 2023). "Preoperative use of antibiotics, ulcerative colitis, lower albumin levels at admission, and delaying surgery for more than seven days were associated with more severe early postoperative complications." (PMID 37878974, 2023). "Protective factors included outpatient treatment, ulcerative colitis, lymphocyte, hemoglobin, platelet, albumin, polypoid lesion (endoscopic feature), and Combo therapy." (PMID 35215942, 2022). "Other studies showed that low serum albumin and high CRP levels are associated with severe disease activity in patients with ulcerative colitis." (PMID 35011900, 2021). "In clinical trials, serum albumin was identified as a significant covariate explaining IIV in clearance for IFX (in ulcerative colitis and Crohn’s disease), ustekinumab, and pertuzumab." (PMID 31817205, 2019). "Serum albumin concentration was found to correlate inversely with IFX elimination in ulcerative colitis patients." (PMID 31817205, 2019). "Two human studies have shown some improvements in albumin and total protein levels after probiotic consumption among ulcerative colitis patients and elderly hospitalised subjects." (PMID 26654906, 2015). "•PON-1, GPx, CAT, albumin, transferrin, and R–SH indicate ulcerative colitis flares." (PMID 39368456, 2024). "The risk factors identified in this study that were associated with the more severe early postoperative complications included preoperative use of antibiotics, diagnosis of ulcerative colitis, lower albumin levels at admission, and a delay in surgery greater than seven days." (PMID 37878974, 2023). "Albumin was reported as a prognostic marker for ulcerative colitis." (PMID 37614903, 2023). "We aimed to analyze the dependence of RUNX3 promoter 2 (P2) methylation level on: age, sex, body mass index (BMI), C-reactive protein (CRP), serum albumin, disease duration, Pediatric Ulcerative Colitis Activity Index (PUCAI), the Paris classification, and exposure to medications." (PMID 36140736, 2022).
urinary tract infection (35 papers, 2006 to 2025). "Our study demonstrates that the procalcitonin/albumin ratio is an early diagnostic predictor that can discriminate between urosepsis and febrile urinary tract infection." (PMID 29995751, 2018). "Increased globulin suggests chronic inflammation consistent with chronic urolithiasis, and in humans, a decreased albumin:globulin ratio serves as a prognostic factor for predicting postoperative febrile urinary tract infection after lithotripsy." (PMID 39457388, 2024). "In group 2, urine tests during the antenatal visits highlighted less albumin, less sugar and fewer urinary tract infections in relation to group 1." (PMID 35617343, 2022). "Plasma biomarkers included glycated hemoglobin, creatinine, cholesterol and triglycerides, as well as urine albumin, transferrin and evidence of urinary tract infection." (PMID 34743740, 2021). "Patients in the urosepsis group had higher procalcitonin/albumin ratios compared to those in the febrile urinary tract infection group [2.254 (0.978, 6.299) vs 0.021 (0.004, 0.095); P < .001]." (PMID 29995751, 2018). "Furthermore, the urine tests are often unavailable due to various reasons: failure to collect urine on the spot at the lab (patients using diapers, incontinence) or inability to quantitate the urine protein/albumin due to concurrent urinary tract infection)." (PMID 38040765, 2023). "Urinary albumin can reflect either glomerular or tubular injury but lacks specificity, with increases also seen with extreme exercise, macroscopic hematuria and urinary tract infection." (PMID 33845861, 2021). "We concluded that patients with larger stone size and preoperative urinary tract infection might have a higher risk of developing SIRS and fever after operation, while a high-normal level of serum albumin might be the protective factor for postoperative fever." (PMID 28261611, 2017). "Therefore, this study aimed to develop a new, early diagnostic predictor that could discriminate between patients with urosepsis and those with febrile urinary tract infections using a combination of initial procalcitonin and albumin levels." (PMID 29995751, 2018). "Based on multivariate logistic analysis, the procalcitonin/albumin ratio [adjusted odds ratio (OR) 1.029, 95% confidence interval (CI) 1.013–1.045, P < .001] was an independent predictor of urosepsis, which allowed for differentiation from patients with febrile urinary tract infections." (PMID 29995751, 2018). "AKI developed more frequently in patients with urinary tract infections (p = .003), with higher SAPS II values (p = .002) and lower albumin values (p = .003)." (PMID 29388454, 2018). "Albuminuria in patients with a urinary tract infection (UTI) has also been studied, which found statistically significant differences in pediatric groups with and without UTI in terms of albuminuria levels and albumin/creatinine ratio." (PMID 29035316, 2017).
gout (34 papers, 2014 to 2026). A condition characterized by painful swelling of the joints, which is caused by deposition of urate crystals. "The potential of PAT101, a recombinant human albumin (rHA)-conjugated variant, was evaluated and compared as a novel gout treatment through various in vivo studies with PAT101 and competing drugs." (PMID 38111075, 2023). "Lower serum albumin levels and worsening secondary hyperparathyroidism were also associated with greater likelihood of gout [OR 1.09 (1.03–1.14) per 1 g/dL decrease in albumin, and OR 1.33 (1.14–1.56) per 50 pg/mL increase in PTH, all p <0.005." (PMID 30682034, 2019). "In patients with gout, serum albumin levels may be related to the risk and outcomes of cardiovascular events." (PMID 41141353, 2025). "Univariate logistic regression showed that sex, mechanical ventilation, gout, white blood cell count, red blood cell width distribution, total bilirubin, albumin, nitrogen, fibrinogen, APTT, NLR, and NIHSS were associated with gastrointestinal bleeding (p < 0.1)." (PMID 40606127, 2025). "In addition, NRBP1 is associated with sodium and albumin excretion and/or metabolism and may also be involved in the pathogenesis of gout." (PMID 39734218, 2024). "In blacks and patients with gout, the correlation between ALB and ALP showed an inverted U-shaped curve with an inflection point of approximately 42 (g/dL)." (PMID 38552093, 2024). "In black people and patients with gout, the relationship between ALB and ALP showed an inverted U-shaped curve, with an inflection point at approximately 42 g/dL." (PMID 38552093, 2024). "A number of previous contradictory studies suggest an interaction between MSU crystals and human serum albumin (ALB) in vitro with reference to the disease of gout." (PMID 34635120, 2021). "The result observed in our investigation supports that ALB prevents initiation of acute gout flares." (PMID 34635120, 2021). "In a C57/BL6 mouse model-based study, the immunobiological effect of IL-38 injection in gouty arthritis was investigated through the administration of albumin-opsonized MSU crystals." (PMID 34830435, 2021). "Considerably more work will need to be done to determine what role does ALB play in the pathogenesis of gout." (PMID 34635120, 2021). "In the final adjusted model, for each 1 g/L lower serum albumin, the likelihood of gout increased by 9%." (PMID 30682034, 2019). "In the current study, we observed for the first time an inverse relationship between serum albumin and gout." (PMID 30682034, 2019). "Adjusting for differences in age and sex, we found that patients with lower kidney function, lower serum albumin, and worsening secondary hyperparathyroidism were more likely to have gout." (PMID 30682034, 2019). "In univariate linear regression analysis, the times of 30-second chair-stand were correlated positively with hemoglobin and serum albumin level, but negatively with age, gout, FTI, ECW/TBW, body mass index, and serum phosphate level." (PMID 27798648, 2016). "In addition, for the first time, our subgroup analysis stratified by race and gout revealed an inverted U-shaped association between ALB and ALP levels in black patients with gout." (PMID 38552093, 2024). "Serum albumin is a negative acute phase reactant, and thus low serum albumin levels may also reflect ongoing systemic inflammation associated with gout." (PMID 30682034, 2019). "Serum albumin and HDL cholesterol levels were significantly lower in both the acute gout attack and intercritical gout groups compared to the control group." (PMID 40722837, 2025). "The target genes of Terpine-4-ol, a main compound of ZP, were overlapped with the gouty arthritis-related genes such as NLRP3, PTGS2, CXCL8, IL6, TNF, IL1B, TLR4, and ALB." (PMID 39861092, 2024). "The results of this study showed that ALB was independently and negatively correlated with ALP, except in black patients and those with gout." (PMID 38552093, 2024).
gout (continued). "Large prospective studies are needed to clarify the relationship between ALB and ALP levels in black patients and those with gout." (PMID 38552093, 2024). "Compared to the HUA group, the gout group had significant higher levels of DBP, SBP, fasting glucose, uric acid and HDL-cholesterol and a lower level of albumin." (PMID 29871692, 2018). "In the intercritical gout group, GDF-15 was moderately and negatively correlated with eGFR (r = −0.53, p < 0.01), weakly and negatively correlated with albumin (r = −0.37, p < 0.05), and weakly and positively correlated with HDL cholesterol (r = 0.40, p < 0.05)." (PMID 40722837, 2025). "A study carried out by Alvsaker found that there was an absence of albumin and alpha globulin in the plasma of some people suffering from gout." (PMID 36359083, 2022). "Gout patients also experienced significantly lower serum albumin concentrations and significantly higher parathyroid hormone concentrations than those without gout, all p<0.001." (PMID 30682034, 2019). "Our study showed an inverse correlation between ALB and ALP levels in most patients with tumors, but not in black patients and those with gout." (PMID 38552093, 2024).
hepatitis C (34 papers, 2013 to 2025). "Serum albumin ≥ 3 was protective and associated with a longer OS across all lines of therapy, whereas a history of hepatitis C infection was associated with improved OS in patients treated with ICI in the 1st-line setting." (PMID 38937977, 2024). "In our study, we found lower (but within normal limits) albumin levels in dialysis patients with hepatitis C with normal total protein levels." (PMID 39456817, 2024). "Patients with hepatitis C or hepatitis B liver illness had a significant decrease in cell-mediated immune function, particularly in the presence of low haemoglobin and albumin." (PMID 39156324, 2024). "Hepatitis C infection, serum levels of albumin, C-peptide, and ABI levels were found to be correlated with BDI (P < 0.05)." (PMID 28455662, 2017). "HCV is an infectious disease that causes acute hepatitis C and may progress to chronic HCV manifested by increased serum total bilirubin, ALT, and AST and reduced serum albumin." (PMID 36466932, 2022). "In early stage HCC, the CSPH group had a higher prevalence of hepatitis C and worse liver function markers (Child–Pugh grade, ALBI score, MELD score, prothrombin time, albumin concentration, and bilirubin concentration) as well as lower platelet count." (PMID 40739081, 2025). "A total of 389 significant genes were common to both hepatitis C and psoriasis, which mainly involved IL6, TNF, IL10, ALB, STAT3 and CXCL8." (PMID 34215260, 2021). "This may be because elevated levels of γ-lactoglobulin are observed in patients with hepatitis C, which may affect normal total protein but not albumin concentrations." (PMID 39456817, 2024).
influenza (34 papers, 2012 to 2025). An acute viral infection of the respiratory tract, occurring in isolated cases, in epidemics, or in pandemics; it is caused by serologically different strains of viruses (influenzaviruses) designated A, B, and C, has a 3-day incubation period, and usually lasts for 3 to 10 days. "The mechanistic rationale is compelling: SP-D multimers traverse disrupted alveolar–capillary barriers proportionally to surface-area loss, mirroring albumin leakage in experimental influenza models." (PMID 41300856, 2025). "Loss of lung integrity during influenza infection has been described and can be monitored by measuring levels of Evans Blue-stained serum albumin in bronchoalveolar lavage fluid (BALF) after intravenous injection as a proxy for increased lung permeability and edema." (PMID 32582220, 2020). "We believe that the effectiveness of albumin administration in preventing glycocalyx degradation in severe influenza or ARDS needs to be further explored." (PMID 34997090, 2022). "Treatment with I3A reduced the PM-exacerbated lung injury in influenza-infected mice, as indicated by reduced concentration of albumin in BALF, which was comparable to the concentrations observed in vehicle-exposed mice." (PMID 34906172, 2021). "SARS-CoV-2 patients had higher LDH (P = 0.035) and serum albumin levels (P = 0.007) than the influenza group." (PMID 34981695, 2021). "To this end, we determined the effects major respiratory secretion components (Na+, K+, Ca2+, cells, albumin IgG, IgM, and mucin) have on the performance of influenza assays including both nucleic acid amplification and rapid antigen assays." (PMID 27870895, 2016). "The antibody responses to influenza vaccination in hospitalized elderly patients were related to nutritional indices such as serum albumin levels." (PMID 26096655, 2015). "Other studies found statistically significant associations between markers of nutritional status including haemoglobin, iron, total protein, serum albumin, vitamin D, and vitamin E and poor response to influenza vaccination." (PMID 26068416, 2015). "e have shown that pulmonary infections such as influenza induce lung injury and disrupt the barrier integrity of lung vasculature and results in increased albumin levels in the alveolar space." (PMID 25923215, 2015). "Previous reports using umbilical vein endothelium have described cytokine production after infection with human influenza or extravasation of albumin from the organs of animals infected with flu." (PMID 23115643, 2012). "Albumin also uses the FcRn recycling mechanisms of IgG so providing that an albumin specific sdAb does not interfere with this interaction it has the potential to improve pharmacokinetics of influenza specific sdAbs." (PMID 33802072, 2021). "Low protein status, characterized by low albumin or pre-albumin levels, but also low iron and vitamin E correlated with lower responses to influenza vaccination in the elderly, thereby highlighting the interrelation between various nutrients and the immune response." (PMID 32471251, 2020). "Of note, controls confirmed the specificity of the antigen-specific Fluorospot assay since negligible spot formation was detected on bovine serum albumin or irrelevant mouse IgG1, κ antigens while spots were evident in wells coated with either of the recombinant influenza antigens." (PMID 32069813, 2020). "Moreover, the aspergillosis group had a significant lower ALB level (34.8 ± 5.7 vs. 31.0 ± 5.3, P = 0.000) than patients with influenza alone." (PMID 33537328, 2020). "The aptasensor was tested in influenza haemagglutinin peptide fragment (HA1), His (a tag on the S1 protein), human serum albumin (HSA), BSA, and artificial saliva." (PMID 38727849, 2024). "Random forest analysis showed that PCT, DD, CRP, respiratory rate, SpO2, albumin, AST/SGOT, calcium, influenza-like symptoms, and ALT/SGPT are the most important variables to predict the need for ICU." (PMID 34496940, 2021).